HIC1 (HIC ZBTB transcriptional repressor 1)
Diseases named in the same sentence as HIC1 in open-access papers (continued):
Sharing a sentence is not in itself a finding about the gene and the disease.
cancer (continued). "Homozygous disruption of Hic1 impairs development and results in embryonic and perinatal lethality in mice, while heterozygous mice develop many different spontaneous malignant tumors including a predominance of epithelial cancers in males and lymphomas and sarcomas in females." (PMID 16248899, 2005). "Finally, our clinical cohorts further validated the expression pattern of HIC1 in cancers." (PMID 37388742, 2023). "In addition, the putative copy-number alterations of HIC1 from genomic identification of significant targets in cancer (GISTIC) included many types, such as deep deletion, shallow deletion, amplification, and gain function, contributing to the alternations of gene expression." (PMID 37388742, 2023). "Overall, these findings indicate that HIC1 may serve different functions in different cancer types, and is a critical prognostic biomarker in several cancers, and monitoring HIC1 expression may help predict the prognosis of cancer patients, which is mutually corroborated by previous studies." (PMID 37388742, 2023). "Notably, the results indicated that HIC1 might be significantly correlated with the sensitivity to several small molecule inhibitors that have been applied in cancer treatment, such as MEK inhibitors trametinib and PD−98059." (PMID 37388742, 2023). "To date, HIC1 mutation in cancers has not been reported, therefore loss of its function mediated by epigenetic modification may drive key stages of human tumorigenesis." (PMID 27107418, 2016). "However, the HIC1 expression was significantly reduced in ESCC samples as compared with that in 3 esophageal benign lesion specimens (all P = 0.000) or in all non-cancer controls (P = 0.000)." (PMID 26510908, 2015). "Although the molecular mechanism underlying HIC1-mediated transcriptional and growth suppression is currently unclear, some researchers proposed that HIC-1 targets E2F-responsive genes responsible for transcriptional regulation and growth suppression in cancer." (PMID 22016618, 2011). "Moreover, aberrant DNA methylation patterns in cancer have been used for the discovery of candidate tumor suppressor genes; e.g. the HIC-1 (hypermethylated in cancer) gene was identified on chromosomal band 17p13.3, which had been described to be aberrantly methylated." (PMID 20017917, 2009). "Hypermethylated in Cancer 1 (HIC1) was originally confirmed as a tumor suppressor and has been found to be hypermethylated in human cancers." (PMID 37388742, 2023). "With regards to chemokines and chemokines receptors, our results revealed significantly positive correlations of HIC1 with CXCL12 and CCR10 in several cancers." (PMID 37388742, 2023). "The genetic alternation frequency of HIC1 was approximately 1.1%, and the genetic alternation frequency was higher than 2.5% in 3 cancer types, including CHOL, SARC, and STAD in TCGA pan-cancer cohort." (PMID 37388742, 2023). "GO analysis found that HIC1 might exert biological functions in calcium ion transport in cancer, and functions on the immune system, including adaptive immune response, activation of immune response, regulation of lymphocyte activation, and T cell activation in cancer biology." (PMID 37388742, 2023). "To explore the expression levels of HIC1 across normal tissues and cancers, we analyzed the HIC1 expression of samples in GTEx, CCLE, and TCGA pan-cancer databases." (PMID 37388742, 2023). "Our findings suggested that HIC1 may serve as a prognostic biomarker, and is related to immune infiltration, immunotherapeutic efficacy, and anti-cancer drug sensitivity in various cancers, thereby providing a theoretical basis for more precise cancer treatment in the future." (PMID 37388742, 2023). "Simultaneous methylation of HIC1 + SFRP1 and DAPK1 + SOX1 exhibited sensitivity of 78.82 and 72.94%, respectively with specificity of 77.14% (AUC = 0.87 for both gene panels) for cancer detection." (PMID 34778370, 2021).
cancer (continued). "The other two-gene cassette comprising of SOX1+HIC1 exhibited combined sensitivity of 80.0% with a specificity of 96% in serum CFDNA [AUC = 0.93] in differentiating malignant EOC samples and cancer-free healthy control serum samples." (PMID 34778370, 2021). "The performance of all the two-gene marker panels (HOXA9 + SOX1) and (HIC1 + SOX1) was found significant and the gene panels differentiated cancer vs normal with a higher accuracy in serum samples." (PMID 34778370, 2021). "As a whole, these data suggest the existence of an intricate relationship between the HIC1 and TGF-β pathways in stromal and cancer cells that deserves to be further investigated." (PMID 33227080, 2020). "Hypermethylated in cancer 1 (HIC1, ZBTB29) is a transcriptional factor that was first identified as a gene that is epigenetically silenced in a variety of human cancers." (PMID 29470558, 2018). "As a control for the efficiency of the decitabine treatment, we determined the mRNA induction of hypermethylated in cancer 1 (HIC1) in SW620 and COLO205 cells, a gene with known promoter hypermethylation in cancer." (PMID 30257705, 2018). "Using this system, here we show simultaneous de novo DNA methylation of genes commonly methylated in cancer, CDKN2A, RASSF1, HIC1 and PTEN in primary breast cells isolated from healthy human breast tissue." (PMID 29133799, 2017). "ESR1, PGP9.5, HIC1 and VGF showed cancer specific methylation pattern in the training set explored, and we chose PGP9.5 and VGF to be further explored in an independent validation set." (PMID 24086249, 2013). "First, we found that ZEB1, SNAI1, SNAI2, TWST1, SMAD3, and HIC1, known to be affected upon EMT in both the RPE and forms of cancer, are preferential repressors in hiPSCs compared to RPE, likely acting as preventive developmental gatekeepers under physiological conditions." (PMID 40565279, 2025). "There was a close relationship of HIC1 with TMB and MSI in different cancers." (PMID 37388742, 2023). "HIC1 is downregulated in PCa and act as a STAT3 inhibitor, which may be a promising target of cancer research and treatment for PCa." (PMID 36741321, 2023). "The three best-performing genes exhibited individual frequencies of 53.0–71.0% in serum CFDNA, and the multiplex assay for these genes were identified to discriminate serum from cancer patients and healthy individuals (area under the curve: HOXA9+HIC1 = 0.95, HIC1+SOX1 = 0.93 and HOXA9+SOX1 = 0.85)." (PMID 34778370, 2021). "Conversely, we demonstrated that only the CROCC-associated signature, which included the DNA homologous recombination factor RAD52, the tumour suppressor gene HIC1 and the repressor of the sonic hedgehog pathway TULP3, had a prognostic value in ER-negative/HER2-negative cancers." (PMID 29559730, 2018). "To examine whether HIC1 is inactive by hypermethylation in NSCLC, we examined the methylation status of HIC1 promoter in cell lines and 10 pairs of NSCLC carcinoma and para-carcinoma tissues by methylation specific PCR (MSP) and bisulfite sequencing PCR (BSP)." (PMID 27107418, 2016). "The results show that HIC1 expression was lower in H292, 95-D, A549, NCI-H1975 and LTEP-a-2 cells and carcinoma tissues than in MRC-5, WI-38 cells and para-carcinoma tissues respectively." (PMID 27107418, 2016). "Correspondingly, the frequency of HIC1 methylation in all non-cancer controls was very low, even lower than that in adjacent normal tissues." (PMID 26510908, 2015). "However, the predictive value of HIC1 for immunotherapeutic efficacy in these cancers has not been illustrated, which should be further investigated in future studies." (PMID 37388742, 2023).
cancer (continued). "The results of KEGG analysis indicated that HIC1 was most commonly involved in the chemokine signaling pathway and cytokine-cytokine receptor interaction, as well as the T cell receptor signaling pathway, calcium signaling pathway, JAK-STAT signaling pathway in different cancer types." (PMID 37388742, 2023). "Besides, we identified several canonical cancer-associated genes that were not enriched in the significantly disturbed pathways, such as ADAMTS9, HIC1, RASAL1, in both the methylation statuses and expression data." (PMID 22140553, 2011). "With regards to the clinicopathological significance of HIC1, our results found that HIC1 was expressed higher in patients with later clinical stages in BLCA, ESCA, and STAD, indicating that HIC1 may function as a biomarker for predicting disease progression for cancer patients." (PMID 37388742, 2023). "Furthermore, our approach identified only genes that are differentially methylated and expressed between cell lines, and not genes that are uniformly suppressed in cancer cells by DNA methylation, such as HIC1 and SOX17, which may be induced by 5AZA." (PMID 25486910, 2014). "Surprisingly, in carcinoma cell lines of acquired doxorubicin resistance (MCF-7_ADR, NCI/ADR-RES), methylation of CGIs from APC, HIC1 and RASSF1 was strongly reduced or completely absent." (PMID 20544021, 2010).
bacterial infection (2 papers, 2018 to 2021). "Our results suggest that HIC1 expression in ILC3s is critically important for immunity to intestinal bacterial infection." (PMID 29470558, 2018). "Together, these results highlight an important role for HIC1 not only in regulating intestinal immune homeostasis but also in mounting proper immune responses to an intestinal bacterial infection." (PMID 29470558, 2018).
infection (2 papers, 2018 to 2020). The state of being infected such as from the introduction of a foreign agent such as serum, vaccine, antigenic substance or organism. "Our results are consistent with a role for NCR+ or TBET+ ILC3s in immunity to C. rodentium as Hic1CD4 mice (deficient for HIC1 in T cells and LTi) are resistant to infection while Hic1Rorc mice (deficient for HIC1 in TH17 cells and all ILC3s) are susceptible." (PMID 29470558, 2018). "To determine the role of HIC1 expression in RORγt+ ILC3s during infection with C. rodentium, we crossed Hic1fl/fl mice with mice expressing Cre recombinase under the control of the Rorc promoter (Hic1Rorc mice)." (PMID 29470558, 2018). "In addition, SDF1 is strongly repressed in MCF7 cells overexpressing HIC1 through infection by an adenoviral vector." (PMID 33227080, 2020). "Furthermore, SDF1 appears strongly repressed in MCF7 cells overexpressing HIC1 through infection by an adenoviral vector." (PMID 33227080, 2020). "In the absence of HIC1, group 3 ILCs (ILC3s) that produce IL-22 are lost, resulting in increased susceptibility to infection with the bacterial pathogen Citrobacter rodentium." (PMID 29470558, 2018). "In this study, we show that deletion of HIC1 in hematopoietic cells results in a significant reduction in the number of αβ and γδ T cells, CD11b+ CD103+ DCs, and ILC3s in the intestine, resulting in susceptibility to infection with the bacterial pathogen Citrobacter rodentium." (PMID 29470558, 2018). "In this manuscript, we show that the atRA-dependent transcription factor Hypermethylated in cancer 1 (HIC1, ZBTB29) is required for ILC homeostasis and function in the steady state as well as following infection with the bacterial pathogen Citrobacter rodentium." (PMID 29470558, 2018).
adenocarcinoma (1 paper, 2024). A common cancer characterized by the presence of malignant glandular cells. "Early studies using the TRAMP mouse model showed stable SIRT1 expression during early carcinogenesis but a significant increase in poorly differentiated adenocarcinomas, correlating with reduced levels of hypermethylated in cancer-1 (HIC1), a regulator of SIRT1." (PMID 39796040, 2024).
neurodevelopmental disorder (1 paper, 2025). A behavioral and cognitive disorder with onset during the developmental period that involves impaired or aberrant development of intellectual, motor, or social functions. "Hypermethylated in cancer 1 (HIC1) is a transcriptional repressor that has been reported to function in several developmental processes, including craniofacial development, a process linked to neurodevelopmental disorders." (PMID 40802760, 2025). "HIC1 has been suggested to be a causal gene in these syndromes; our findings implicate HAR123 as also being a candidate to have a role in these neurodevelopmental disorders." (PMID 40802760, 2025).
HIC1 also shares sentences with these, for which no sentence is quoted: diabetic kidney disease (3 papers); esophageal cancer (3); hepatocellular carcinoma (3); colonic polyps (2); colorectal (2); pheochromocytoma (2); renal cell carcinoma (2); adrenocortical carcinoma (1); anal carcinoma (1); autism (1); autoimmune disease (1); breast fibroadenoma (1); Canavan disease (1); cervical squamous cell carcinoma (1); cholangiocarcinoma (1); choriocarcinoma (1); chronic gastritis (1); chronic hepatitis (1); Cirrhosis (1); diffuse large B-cell lymphoma (1); endocervical adenocarcinoma (1); esophagitis (1); Ewing sarcoma (1); gastric tumors (1); hyperparathyroidism (1); kidney chromophobe (1); lentivirus infection (1); Lissencephaly (1); lung squamous cell carcinoma (1); lymphoid neoplasm (1).
A further 19 diseases each share a sentence with HIC1 in 1 paper.